CARD9 (caspase recruitment domain family member 9)
Diseases named in the same sentence as CARD9 in open-access papers (continued):
Sharing a sentence is not in itself a finding about the gene and the disease.
kidney injury (1 paper, 2024). Trauma to the kidney. "We demonstrate that CARD9 deficiency-aggravated acute kidney injury and renal ferroptosis in disseminated C. tropicalis infection results from decreased MDSCs accumulation and SLC7A11 expression in the kidneys." (PMID 38566195, 2024). "Finally, inhibition of mitochondrial OXPHOS or ferroptosis alleviates CARD9 deficiency-aggravated acute kidney injury during disseminated C. tropicalis infection." (PMID 38566195, 2024).
limb ischemia (1 paper, 2023). A ischemia that involves the limb. "The present study was designed to test the hypothesis that CARD9-mediated signaling is critically involved in PM exposure-induced ROS production and impaired recovery following limb ischemia." (PMID 36860276, 2023). "The present study was designed to test the hypothesis that CARD9 signaling is critically involved in PM exposure-induced oxidative stress and impaired recovery of limb ischemia." (PMID 36860276, 2023).
MALT lymphoma (1 paper, 2022). An indolent, extranodal type of non-Hodgkin lymphoma composed of small B-lymphocytes (centrocyte-like cells). "One possible explanation for the high protein levels of CARD9 in U-RT1 is gene amplification, as already described in MALT-lymphoma." (PMID 35158799, 2022).
meningitis (1 paper, 2015). A disorder characterized by acute inflammation of the meninges of the brain and/or spinal cord. "This is in contrast to the induction of CXC chemokines in the Candida-infected CSF of another patient without CARD9 deficiency who developed meningitis post-Ommaya reservoir placement at NIH, whose CSF was chemotactic toward neutrophils ex vivo." (PMID 26679537, 2015).
mycobacterial infection (1 paper, 2021). "Furthermore, TREM2 deletion enhances Mincle-induced macrophage activation in vitro and inflammation in vivo and accelerates the elimination of mycobacterial infection, suggesting that TREM2-DAP12 signaling counteracts Mincle-FcRγ-CARD9-mediated anti-mycobacterial immunity." (PMID 33863908, 2021).
Mycobacterium infection (1 paper, 2019). Infections with bacteria of the genus Mycobacterium. "Dectin-3 can also recognize TDM and induce Mincle expression upon Mycobacterium infection via CARD9–Bcl-10–MALT1-dependent NF-κB activation and the increased Mincle expression can enhance the ability of host innate immune system to sense Mycobacterium infection." (PMID 31687150, 2019).
myocarditis (1 paper, 2022). Myocarditis is a condition that is characterized by inflammation of the heart muscle (myocardium). "In myocarditis induced by coxsackievirus B3 (CVB3), a single-stranded RNA virus, CARD9-knockout (KO) mice showed less myocardial inflammation and structural disorganization." (PMID 35173530, 2022). "In fact, CARD9 also plays a role in both infectious and non-infectious pathophysiological processes of heart injuries, including myocarditis, myocardial ischemia reperfusion (I/R) injury, and angiotensin II (Ang II)-induced cardiac remodeling and dysfunction 10-12." (PMID 35173530, 2022).
necrotizing enterocolitis (1 paper, 2014). Necrotizing enterocolitis (NEC) is a devastating disease that affects mostly the intestine of premature infants. "Lastly, we examined whether there were any differences in the frequency of the polymorphisms of NOD2, CARD9, RAC1 and ATG16L1 in relation to inflammatory etiologies of IF such as in the cases with necrotizing enterocolitis (NEC)." (PMID 24465786, 2014).
oral candidiasis (1 paper, 2015). Infection of the mucosal lining of the mouth with the fungus Candida albicans. "IL-17 signaling is essential for immunity in oral candidiasis, whereas CARD9 is largely dispensable." (PMID 26336150, 2015).
Pneumocystis pneumonia (1 paper, 2025). "Our work further underscores the role of CLR signaling through CARD9 in mediating lung inflammation during Pneumocystis pneumonia, which can promote respiratory impairment during severe disease." (PMID 39745390, 2025). "In addition, such strategies can also be combined with inhibition of CARD9 signaling to concurrently control exuberant and injurious lung inflammation during Pneumocystis pneumonia." (PMID 39745390, 2025).
pulmonary fungal infections (1 paper, 2016). "This dichotomy observed in mice between the Card9-dependence for protection against molds and yeasts may help explain why human CARD9 deficiency does not appear to associate with pulmonary fungal infections, despite the continuous environmental exposure to fungal spores." (PMID 27092298, 2016).
pulmonary tuberculosis (1 paper, 2014). A bacterial infection that affects the lungs and is caused by Mycobacterium tuberculosis. "An early role for the cytosolic adaptor caspase recruitment domain family, member 9 (Card9) in pulmonary tuberculosis was demonstrated when Card9−/− mice were shown to succumb rapidly to aerosol infection by Mycobacterium tuberculosis H37Rv." (PMID 25002863, 2014).
renal fibrosis (1 paper, 2012). A final common manifestation of a wide variety of chronic kidney diseases characterized by glomerulosclerosis and tubulointerstitial fibrosis. "Tim3, DAP-12, Card-9, DC-SIGN and MR2 were further up-regulated during renal fibrosis." (PMID 22949850, 2012).
respiratory infection (1 paper, 2024). "Several groups have reported that Card9-deficient mice are susceptible to respiratory infection with various cryptococcal strains." (PMID 38921420, 2024).
systemic lupus erythematosus (1 paper, 2024). An autoimmune multi-organ disease typically associated with vasculopathy and autoantibody production. "Some of the loci involved in IgAN, such as CARD9 or HORMAD2, are shared with IBD, and have also been associated with immune-mediated diseases, such as Systemic Lupus Erythematosus (SLE)." (PMID 39768250, 2024).
thymus (1 paper, 2021). "Mechanistically, the flo8 mutant-induced Dectin-2/CARD9-mediated IL-10 production in DCs and macrophages to block thymus atrophy by inhibiting the C. albicans-induced apoptosis of thymic T cells, which facilitated the continuous output of naive T cells from the thymus to the spleen." (PMID 33154574, 2021).
thyroid cancer (1 paper, 2022). "Interestingly, there is relative lack of knowledge on the role of the remaining three genes, i.e. IMMP2L, RARRES1 and CARD9-SNAPC4 in thyroid cancer." (PMID 35976137, 2022).
ulcer (1 paper, 2022). "For example, Clostridium innocuum invasion led to intestinal creeping fat, Debaryomyces Hansenii delayed ulcer healing through the IFN-1-STAT1-CCL5 signaling pathway, and Malassezia restricted inflammation through the CARD9 pathway." (PMID 36275466, 2022).
viral myocarditis (1 paper, 2022). Myocarditis that is caused by an infection with a viral agent. "In a Coxsackievirus B3 (CVB3)-induced viral myocarditis mouse model, CARD9 deletion downregulated the mRNA and protein expression of TGF-β, IL-17A, and BCL-10, thereby ameliorating the CARD9-involved potent inflammation response." (PMID 36439825, 2022).
vulvovaginal candidiasis (1 paper, 2023). Infection of the vulva and vagina with a fungus of the genus CANDIDA. "STRING analysis demonstrated that SYK, TLR4, CARD9, and TLR2 are involved in vulvovaginal candidiasis and infectious disease pathways." (PMID 37238269, 2023).
Zinc deficiency (1 paper, 2017). A deficiency of the essential metal Zinc; an essential cofactor for many enzymes. "HFD and zinc deficiency synergistically induce ORCH by increasing oxidative stress‐mediated activation of BCL10/CARD9/p38 MAPK signalling." (PMID 28158919, 2017). "In the present study, zinc deficiency exacerbated BCL10 and CARD9 expression in obese mice, while zinc supplement reduced the BCL10 and CARD9 levels." (PMID 28158919, 2017). "Administration of SB203580 to HFD mice or specific siRNA in palmitate‐treated cardiomyocytes eliminated the HFD and zinc deficiency activation of p38 MAPK, but did not significantly impact the expression of BCL10 and CARD9." (PMID 28158919, 2017).
infection (54 papers, 2013 to 2025). The state of being infected such as from the introduction of a foreign agent such as serum, vaccine, antigenic substance or organism. "At day 4 after infection, neutrophils and additional Ly6C+ monocytes were recruited to the CARD9-deficient brain." (PMID 40424070, 2025). "Our current mouse model revealed a neutrophil response to C. albicans in the brain following infection in CARD9-deficient mice." (PMID 40424070, 2025). "Card9 deficiency has also been associated with infection by a variety of other fungi including Trichophyton sp., Phialophora verrucosa, Exophiala sp., Aspergillus fumigatus, Corynespora cassiicola, and others." (PMID 38921420, 2024). "To further characterize the consequences of Card9 deficiency on anti-cryptococcal immune responses, we used a well-established model of intratracheal infection with 104 CFU of C. neoformans 52D, a moderately virulent serotype D clinical isolate." (PMID 38921420, 2024). "Genetic deletion of Card9 in mice confers susceptibility to infection with several fungal pathogens." (PMID 38921420, 2024). "To date, we cannot explain why the CARD9 deficiency plays a context-dependent role in different infections, even with the same type of pathogen." (PMID 38473845, 2024). "CARD9 mediates distinct tissue-specific responses in infections caused by C. albicans, C. parapsilosis, and C. neoformans." (PMID 38473845, 2024). "Card9 deficiency was first reported in 2009 in a consanguineous family with severe infections caused by the normal human commensal organism Candida sp." (PMID 38921420, 2024). "The first report to implicate Card9 in host susceptibility to C. neoformans demonstrated a higher lung fungal burden at day 5 and day 14 post-infection with 106 colony-forming units of C. neoformans 3501 in Card9-deficient mice." (PMID 38921420, 2024). "CARD9 plays a critical role in host immunity against infections caused by fungi, bacteria, and viruses." (PMID 38473845, 2024). "Human CARD9 mutations are particularly associated with susceptibility to Candida albicans infection of the central nervous system, al-though infection with other uncommon fungal strains has also been reported." (PMID 38921420, 2024). "Three cases of CARD9 deficiency causing infection with this fungus had been reported, and the treatment of antifungal infection was ineffective in two of them." (PMID 37448776, 2023). "CARD9 is critically involved in both innate and adaptive immune responses to infections with fungi, bacteria, and viruses, and closely associated with infiltration and activation of immune cells and productions of pro-inflammatory cytokines." (PMID 35432375, 2022). "CARD9 deletion also leads to a deficiency of anti-infection feedback loop against intracellular DNA virus with impaired inflammatory responses." (PMID 35432375, 2022). "We report a patient with Dectin-1 deficiency with severe C. cassiicola phaeohyphomycosis, an infection previously reported in inherited CARD9 deficiency." (PMID 36377664, 2022). "Data show that CARD9 deficiency is able to alter cytokine expression in the brain with temporarily increased pro-inflammatory cytokine responses early after infection." (PMID 34209576, 2021). "CARD9 has been shown to be essential for M1-polarization of myeloid cells, supporting the view that the loss of CARD9 enhances M2-polarization following TMEV infection." (PMID 34209576, 2021). "For example, multiple different loss-of-function mutations in CARD9 have been associated with autosomal recessive inheritance of susceptibility to invasive infections by fungi, including Candida spp., dermatophytes, and fungal plant pathogens." (PMID 32185141, 2020). "In the last decade, infections associated with CARD9 deficiency are more reported due to the advent of genome sequencing." (PMID 30369919, 2018).
infection (continued). "We found that the burdens in lung and brain were significantly higher in CARD9-deficient mice than those in WT mice on day 3 and 14 after infection with C.g-B strain ATCC32609." (PMID 30131805, 2018). "We also discuss the effect of CARD9 genetic mutations on the in vivo immune response, and highlight clinical advances in non-infection inflammation." (PMID 29352133, 2018). "Upon pulmonary C.n-AD and C.g-B infection, Dectin-3- and CARD9-deficient mice were highly susceptible and showed augmented lung injury due to impairment of alveolar macrophage accumulation and killing activities." (PMID 30131805, 2018). "We investigated several CARD9 single nucleotide polymorphisms (SNPs) and defined how this candidate gene influences infection phenotypes, notably progression to active TB, as well as the extent of pulmonary inflammation during active disease." (PMID 27684065, 2016). "This phenotype resembles that of the Card9−/− mice; however, these animals presented with greater pathology, and all of the animals died shortly after infection, a severity that was linked to defects in IL-10 production." (PMID 25674984, 2015). "As shown, CARD9−/− mice administered etanercept were only slightly (albeit significantly) more susceptible to infection compared with controls." (PMID 26336150, 2015). "Taken together, these results show that, while both CARD9-deficient mouse strains develop chronic CNS candidiasis with increasing brain fungal burden, Card9–/– mice develop a more severe phenotype (skull deformity) late in infection." (PMID 40424070, 2025). "These ECVs, which provide some context for interpreting an MIC value, are an additional tool in selecting antifungal therapy while also considering factors such as pharmacokinetics and pharmacodynamics, site of infection, lesion size, and patient’s health status (e.g., CARD9 mutations)." (PMID 40183549, 2025). "During infections, CARD9-deficient humans and mice have an increased pathogen burden." (PMID 38473845, 2024). "Card9-deficient mice also had reduced expression of Il17a and the associated transcription factor RORγτ in lung homogenates at day 7 post-infection compared to wild-type mice; however, Il—17a-deficient mice actually had a significantly lower lung fungal burden at day 14 post-infection." (PMID 38921420, 2024). "A CARD9 deficiency impairs the production of inflammatory cytokines and chemokines as well as migration and infiltration, thereby increasing susceptibility to infections." (PMID 38473845, 2024). "Finally, following challenge with the highly virulent C. neoformans H99 strain, wild-type C57BL/6 mice survived longer than Card9-deficient mice (median survival 21 days versus 26 days) but all mice succumbed by day 29 post-infection." (PMID 38921420, 2024). "In addition, the absence of differential fungal growth in the brain despite significant differences in survival of wild-type and Card9-deficient mice following LW10 or H99 infection is unexplained." (PMID 38921420, 2024). "This review aims to elucidate the role of CARD9 in infections caused by various pathogens." (PMID 38473845, 2024). "Taken together, these findings demonstrate that Card9 broadly regulates the expression of inflammatory, Th1-, Th2-, and Th17-associated cytokines as well as several chemokines in mouse lungs following intratracheal infection with C. neoformans." (PMID 38921420, 2024). "To characterize the effect of Card9 mutation on lung pathology after challenge with C. neoformans, we analyzed tissue sections from Card9em1Sq and Balb/c mice at serial time points after infection." (PMID 38921420, 2024). "We hypothesized that the effect of Card9 deficiency might be confounded by the natural susceptibility of C57BL/6 inbred mice to progressive infection with C. neoformans 52D." (PMID 38921420, 2024).
infection (continued). "AR complete CARD9 deficiency has been linked to impaired cytokine and chemokine production, ineffective clearance of fungi by neutrophils, and impaired neutrophil recruitment at the sites of infection." (PMID 35628702, 2022). "Defective CARD9 signaling in DCs impairs T cell responses, making it more susceptible to infection." (PMID 35432375, 2022). "In addition to the well-known role in various antimicrobial mechanisms, CARD9 contributes to the pathogenesis of some diseases associated with infections." (PMID 35432375, 2022). "In late phase of infection, pathogens could spread to brain, lungs, liver, spleen, kidney, and draining lymph nodes in CARD9 deficient mice." (PMID 35432375, 2022). "Finally, testing Syk and CARD9 agonists in the setting of experimental infections by common pathogenic Candida species will provide valuable information on the curative prospects of Syk/CARD9 signaling on a species-specific scale." (PMID 34465030, 2021). "Notably, several patients with CARD9 mutations suffered from an aggressive infection of the rare species P. verrucosa s.str." (PMID 33572699, 2021). "From a genetic perspective, we speculate that the patient’s second sister may have also had a complex heterozygous CARD9 mutation, dying as a result of TM infection." (PMID 34234782, 2021). "Upon pulmonary C.n-AD and C.g-B infection, Dectin-3- and CARD9-deficient mice were highly susceptible and showed augmented lung injury due to impairment of AM accumulation and killing activities, and subsequent productions of pro-inflammation cytokines and chemokines." (PMID 30131805, 2018). "Moreover, CARD9 deficiency completely blocked AM accumulation in the lungs at day 1 after infection with C.n-AD strain WM628 and C.g-C strain NIH312." (PMID 30131805, 2018). "Moreover, CARD9-deficient mice exhibited higher fungal burdens in lungs than WT mice after intratracheal infection with C.n-AD strain WM628, C.g-C strain NIH312, and C.n-D strain WM629 for 3 days (p < 0.01)." (PMID 30131805, 2018). "However, some organs are unaffected by CARD9 deficiency during infection by certain pathogens." (PMID 38473845, 2024). "However, CARD9 signaling varies depending on the pathogen causing the infection." (PMID 38473845, 2024). "The need for Dectin-3 may explain why CARD9-deficient mice are more susceptible to infection." (PMID 32545735, 2020). "Since the IL-17/IL-22 pathway has also been shown to promote neutrophil recruitment into infected tissues, and some CARD9-deficient patients have reduced Th17 cells in the peripheral blood, we determined the levels of IL-17 and IL-22 in the brains of WT and Card9-/- mice following infection." (PMID 26679537, 2015). "In our current study, we also compared the Clec7a−/−Fcer1g−/− versus Card9−/− and WT animals at 30 and 60 days post-infection." (PMID 39745390, 2025). "Although Card9−/− displayed markedly increased P. murina (Pm) burdens compared with WT infection mice as we published previously, we further noted even significantly greater P. murina burdens in the Clec7a−/−Fcer1g−/− PCP mouse model quantitated by qPCR." (PMID 39745390, 2025). "Taken together, these findings indicate that Card9-dependent processes have a significant effect on lung recruitment of monocytes, dendritic cells, and neutrophils following C. neoformans 52D infection in Balb/c mice." (PMID 38921420, 2024). "CARD9-mediated signaling is critically involved in diverse cell functions and host defenses against infections of fungi, bacteria, and viruses." (PMID 35432375, 2022). "This is quite different from the function of Card9 in fungal signal transduction, where Card9 plays a central role in driving pro-inflammatory signal transduction responses to infection." (PMID 35618701, 2022). "Herein, we briefly describe previous findings and review recent studies to further elucidate the inner relationship between CARD9 and infection immunity." (PMID 36439825, 2022).